FOXP3 (forkhead box P3)
Diseases named in the same sentence as FOXP3 in open-access papers (continued):
Sharing a sentence is not in itself a finding about the gene and the disease.
polyendocrinopathy (102 papers, 2006 to 2026). "A total of 38.4% had CVID, 46% had a combined immunodeficiency, 15.3% had CGD, and one patient had FOXP3-deficient immune dysregulation, polyendocrinopathy, and enteropathy X-linked (IPEX) syndrome." (PMID 36675441, 2023). "Scurfy mice with a mutation in FOXP3 exhibit a defect in their suppressive capacity, resulting in multiple autoimmune phenomena resembling human immunodysregulation, polyendocrinopathy, enteropathy, X-linked (IPEX) syndrome." (PMID 36346673, 2022). "Two patients (15.3%) had CGD, and a single patient had FOXP3-deficient immune dysregulation, polyendocrinopathy, enteropathy X-linked (IPEX) syndrome." (PMID 36211419, 2022). "The short arm of X harbors the short stature-homeobox gene (SHOX on Xp22.33) and lymphogenic gene (forkhead box P3, FOXP3 on Xp11.23), which are associated with stature and immunodeficiency or polyendocrinopathy." (PMID 32684981, 2020). "Forkhead box protein 3 (FOXP3) is a critical transcription factor for CD4+ Foxp3+ Tregs and pathogenic variants in FOXP3 leads to immunodysregulation, polyendocrinopathy, enteropathy X-linked (IPEX) syndrome and prototype of a group of disorders called PIRD (Primary Immune Regulatory Disorders)." (PMID 34122435, 2021). "Immunodysregulation, polyendocrinopathy, enteropathy, and X-linked (IPEX) syndrome, which is caused by mutations in the FOXP3 gene, is characterized by neonatal autoimmune type 1 diabetes, polyendocrinopathy, autoimmune hemolytic anemia, autoimmune enteropathy, and skin rash." (PMID 29535721, 2018). "Immune dysregulation, polyendocrinopathy, enteropathy, X-linked (IPEX) syndrome is a rare X-linked recessive immunodeficiency caused by mutations in the forkhead box protein 3 (FOXP3) gene." (PMID 36479284, 2022). "Immune dysregulation, polyendocrinopathy, enteropathy, X-linked (IPEX) syndrome is a rare life threatening congenital autoimmune disorder caused by mutations in the forkhead box protein 3 (FOXP3) gene." (PMID 29312905, 2017). "In humans, Foxp3 deficiency also leads to a systemic autoimmune disease known as IPEX (immune dysregulation, polyendocrinopathy, enteropathy X-linked syndrome)." (PMID 19821980, 2009). "The involvement of Tregs was suggested by the analysis of patients with immunodysregulation, polyendocrinopathy, enteropathy, X-linked (IPEX), who harbor dysfunctional Tregs due to loss-of-function FOXP3 mutations and show elevated frequencies of circulating autoreactive mature naive B cells." (PMID 34813502, 2022). "Immune dysregulation, polyendocrinopathy, enteropathy, X-linked (IPEX) syndrome characterizes complex autoimmune reactions beginning in the perinatal period and caused by dysfunction of the transcription factor forkhead box P3 (FOXP3)." (PMID 33668198, 2021).
ovarian carcinoma (101 papers, 2006 to 2025). A malignant neoplasm originating from the surface ovarian epithelium. "In ovarian cancer, FoxP3 Tregs were strongly associated with disease stage, and increased infiltration of FoxP3 Tregs in advanced or highly differentiated ovarian tumors suggested improved survival." (PMID 40216744, 2025). "Specifically, FoxP3 Tregs showed prognostic effects in breast and ovarian cancer, where FoxP3 Tregs were associated with estrogen receptor (ER) status." (PMID 40216744, 2025). "Studies on FOXP3 polymorphisms in ovarian cancer identified SNPs rs3761548A/C and rs5902434del/ATT as associated with epithelial ovarian tumor susceptibility and prognosis." (PMID 40703514, 2025). "The ovarian cancer environment caused migration of CTLA4+ FOXP3+ GITR+ Tregs via the chemokine CCL22, secreted by tumor cells and TAMs, and its receptor CCR4, expressed by infiltrating Tregs." (PMID 28275576, 2017). "In the absence of the study by Mhawech-Fauceglia, the estimated pooled HR indicated that the high CD8+/FoxP3+ ratio was associated with improved OS/DSS in ovarian cancer patients (HR, 0.61; 95%CI, 0.41-0.92; PHR=0.02; I2=75.5%; random effects model)." (PMID 28152503, 2017). "On one side it is known that FOXP3 positive regulatory T (Treg) cell infiltration is associated with decreased survival in ovarian cancer." (PMID 27531373, 2016). "An increase in the Tr1 cell : FoxP3+ tTreg ratio was associated with longer survival in a small clinical study of four recurrent ovarian cancer patients undergoing adoptive T cell transfer with autologous IL-10 and interferon gamma (IFN-γ)-producing Teff." (PMID 27509527, 2016). "In high grade or advanced ovarian cancer, high numbers of FoxP3+ Tregs infiltrating were found to be associated with improved survival, whereas the pooled analyses of the remaining studies showed FoxP3+ Tregs were associated with poor prognosis." (PMID 26462617, 2015). "Therefore, many studies have suggested that higher Foxp3 Treg infiltration is associated with poor prognosis in various malignancies including breast, lung, cervical, oral cavity and ovarian cancers." (PMID 32758195, 2020). "However, cells expressing FoxP3, a transcription factor associated with T regs, have also been observed as beneficial for ovarian cancer patient survival outcomes." (PMID 24376535, 2013). "Moreover, the number of CD4+Foxp3+ Tregs was higher in our B7-H4-positive specimens than that in our B7-H4-negative ones, which reflects a previously reported positive association between Tregs and B7-H4 in ovarian cancers." (PMID 34651047, 2021). "Moreover, a high number of FoxP3+ cells was found to be associated with a poor prognosis, increased invasiveness and probability of metastasis occurrence in several solid tumors, such as renal cell carcinoma and ovarian cancer." (PMID 28885584, 2017). "Prior study has found that pDCs promote the expansion of Foxp3+regulatory T cells via the ICOSL-ICOS axis in ovarian cancer, thereby mediating immunosuppression and facilitating tumor progression." (PMID 41567210, 2025). "The primary aim of this study was to investigate the modulation of FOXP3 gene expression in OVCAR3 ovarian cancer cells following exposure to rosmarinic acid and doxorubicin." (PMID 39770446, 2024). "This research not only deepens our understanding of FOXP3’s role in ovarian cancer, but also offers a potential pathway for overcoming chemoresistance and advancing personalized cancer therapies." (PMID 39770446, 2024).
ovarian carcinoma (continued). "By exploring these molecular and genetic pathways, we aimed to provide insights into the therapeutic potential of targeting FOXP3 in combination with chemotherapeutic agents to overcome resistance in ovarian cancer cells." (PMID 39770446, 2024). "Immunohistochemistry analysis revealed a positive correlation of CD8 and FOXP3 staining with activin A at the protein level in both primary and metastatic epithelial ovarian cancer samples." (PMID 39248018, 2024). "VISTA, CTLA4, PDL1, PD1, CD8, CD4, and FOXP3 mRNA extracted from 429 patients with ovarian cancer in the Cancer Genome Atlas (TCGA) database was included as a validation cohort." (PMID 38634058, 2024). "Recently, pre-treatment M2 macrophage infiltration was associated with poor response to chemotherapy and shorter DFS in ESCC patients, whereas the presence of FoxP3+ TILs was also related to a worse prognosis in ovarian cancer patients." (PMID 35158822, 2022). "High expression of GrB and specifically high GrB/Foxp3 ratio in ovarian cancer tissue after the neoadjuvant chemotherapy was reported in patients with favorable progression-free survival." (PMID 33136178, 2021). "We aimed to clarify the role of lncRNA X-inactive specific transcript (XIST)/miR-149-3p/forkhead box P3 (FOXP3) axis in ovarian cancer (OC) cell growth." (PMID 33542185, 2021). "As a result, any single immune marker was not related to survival rate, including CD8, which was a representative marker of CTL; FoxP3 in Treg; and PD-L1, which has been known as a prognostic marker in ovarian cancer but is under debate." (PMID 34502561, 2021). "In ovarian cancer, increased expression of FoxP3 has been shown to correlate with reduced survival time and disease progression." (PMID 34900746, 2021). "On the one hand, CD4+ T cells accumulating in tumors often belong to the Foxp3 expressing regulatory T cell subset, which can be induced by TAMs through IL-10 release as demonstrated in tumor tissues of ovarian cancer patients." (PMID 30853959, 2019). "The detection of conventional and Tbet+ Treg populations in OPSCC and CxCa confirmed studies reporting the presence of CD4+Foxp3+ T cells co-expressing Tbet in chronic hepatitis C driven liver cancer, oral squamous cell carcinoma and ovarian cancer." (PMID 30658697, 2019). "Immunocompetent TILS and FoxP3 T regulatory cells, are strategically located in ovarian cancer tissue." (PMID 29843813, 2018). "Both TGF-β and ovarian cancer conditioned medium upregulate Foxp3 expression in human CD4+IL-17A+ TALs compared with control and Th17-driving conditions." (PMID 28290453, 2017). "In line with the mouse data demonstrating the transdifferentiation of Th17 cells into IL-17negFoxp3+ cells, Foxp3 expression is induced in human IL-17A-producing ovarian cancer TALs when CD4+IL-17+ cells are restimulated under Treg-driving conditions." (PMID 28290453, 2017). "Apart from Helios, the percentage of PD1+ Foxp3+ CD4+ cells in ovarian cancer of RORγt−/− mice (42.4±2.97% (control) and 24.55±4.89 (RORγt−/−), n=5 per group) is significantly lower." (PMID 28290453, 2017). "Although IL-17 is secreted by CD4+ T cells and CD68+ macrophages in ovarian cancer, in other types of cancer, a population of FoxP3+ regulatory T cells (Treg), that under certain conditions express IL-17, plays a critical role in the regulation of CSCs." (PMID 28819364, 2017). "CD4+ T cells infiltrating the ovarian cancer ascites demonstrate a propensity towards either Foxp3-expressing or IL-17A-producing phenotype, implying that the developmental pathways of Treg and Th17 cells are mutually exclusive." (PMID 28290453, 2017). "Similar to the mouse IL-17A+Foxp3+ T cells, human ovarian cancer ascites-infiltrating IL-17A+Foxp3+ T cells show upregulation of neuropilin, GARP and ST2 compared with IL-17A+Foxp3neg T cells, and present a phenotype similar to IL-17AnegFoxp3+ T cells." (PMID 28290453, 2017).
ovarian carcinoma (continued). "Compared with the Foxp3+ CD4+ T cells in ovarian cancer ascites of wild-type mice, the percentage of Helios+ subset of Foxp3+ cells infiltrating cancer ascites of RORγt−/− mice is significantly reduced." (PMID 28290453, 2017). "For example, in an ovarian carcinoma study, the majority of FoxP3+ TI Tregs upregulated the Th1 master transcription factor, T-bet, and expressed CXCR3 enabling them to migrate in response to CXCL10." (PMID 27509527, 2016). "Our stratified analyses demonstrated that the prognostic value of FoxP3+ Tregs in ovarian cancer varied depending on tumor stages." (PMID 26462617, 2015). "We stained 210 human ovarian carcinoma samples immunhistochemically for FoxP3 and CD8 to identify the impact different immune cell patterns have on generally accepted prognostic variables as well as on overall survival." (PMID 25365237, 2014). "FoxP3+ expression in these lymphoid aggregates surrounding the tumor bed was found to be an independent prognostic factor for patients with ovarian carcinoma." (PMID 25365237, 2014). "Second, over-expression of FOXP3 in glioma, breast, prostate and ovarian cancer cell lines induces profound growth inhibition in vitro and in vivo." (PMID 24406338, 2014). "While the expansion and the suppressive function of these Foxp3+ICOS+Treg cells was strictly dependent on ICOS-ligand (ICOS-L) stimulation provided by tumor plasmacytoid dendritic cells (pDCs) in ovarian cancer and BC." (PMID 24124553, 2013). "In contrast, the presence of the CD4-positive regulatory subtype of T lymphocytes (Treg; CD4+CD25+FoxP3+) seems to reduce tumour-specific immunity and results in poorer survival of patients with ovarian carcinomas." (PMID 19861998, 2009). "In contrast, the presence of the CD4-positive regulatory subtype of T lymphocytes (Treg; CD4+CD25+FoxP3+) seems to reduce tumour-specific immunity and results in a poorer survival of patients with ovarian carcinomas." (PMID 19861998, 2009). "Another study on ovarian cancer patients found that not only intraepithelial CD8+ tumor-infiltrating lymphocytes but also a high CD8+/CD25+FOXP3+ regulatory T cell ratio (i.e., low relative FOXP3 infiltration) is associated with a favorable prognosis." (PMID 17166272, 2006). "In the context of ovarian cancer, such analyses can reveal how simultaneous modulation of FOXP3 and EGFR signaling may influence immune checkpoint regulators, including PD-1/PD-L1 and CTLA-4, which are crucial in tumor immune evasion." (PMID 41301890, 2025). "Understanding the role of FOXP3, a crucial regulator of immune tolerance, in the context of ovarian cancer cells could offer valuable insights into its potential as a therapeutic target." (PMID 39770446, 2024). "Furthermore, in ovarian cancer cells, inhibitory properties in proliferation, migration, and invasion were observed when FOXP3 was upregulated." (PMID 36672296, 2023). "Additionally, correlations with interferon beta, PDL-1 and FOXP3 levels were detected in ovarian cancer." (PMID 36068443, 2023). "Further to this, the ratio of CD4+CD25+FOXP3+ Tregs to effector CD8+ T cells in the tumor can be an important predictor of mortality in ovarian cancer, with higher amounts of Tregs compared to the effector CD8+ T cells being correlated with poorer clinical outcomes and reduced long-term survival." (PMID 36428581, 2022). "Additionally, both TApDCs and ICOS+ Foxp3+ Tregs predict disease progression in epithelial ovarian cancer patients." (PMID 34737750, 2021). "Moreover, the ovarian cancer microenvironment can induce migration of CTLA4+ FOXP3+ GITR+ Tregs via the chemokine CCL22 and its receptor CCR4, the latter expressed by infiltrating Tregs." (PMID 28929459, 2018). "In high-grade epithelial ovarian cancers (EOCs) patients, CD20+ infiltrates are strongly associated with all three T-cell subsets (CD3, CD4, and CD8), as well as T-cell differentiation markers TIA-1, Granzyme B, and FoxP3." (PMID 27331871, 2016).
ovarian carcinoma (continued). "Combined with two previous studies, which showed that gastric or ovarian cancer cells could induce the conversion of CD4+CD25− T cells into CD4+FoxP3+ Treg in vitro, we thought that most cancer cells might have the ability of the induction of Treg." (PMID 22174855, 2011). "However, the number of studies and clinical trial examples demonstrating the effects of the FOXP3 signaling pathway on cancer growth and proliferation in ovarian cancer is very limited, and the effects of related molecules/pathways on tumor metastasis remain to be investigated." (PMID 39770446, 2024). "It has been described that miR-125b could induce autophagy through its interaction with Foxp3 in thyroid cancer cells and modulate autophagy in drug-resistant ovarian cancer cells using directly targeted MAP kinase interacting serine/threonine kinase 2 (MKNK2)." (PMID 37834215, 2023). "Many studies about the impact of NAC on TIME in ovarian cancer have been published, and have generally demonstrated that the levels of CD3/CD8 T cells and CD68 tumor-associated macrophages increased after NAC, while Foxp3 regulatory T cells decreased after NAC." (PMID 35565437, 2022). "Previous data derived from several in vitro studies increasingly pointed to the critical role of FOXP3 as a tumor suppressor, including repressing tumor cell proliferation, promoting apoptosis and reducing cell invasion in at least breast, prostate and ovarian carcinoma models." (PMID 28903735, 2017). "The main focus of our study was to examine the association of tumor infiltrating CD4+CD25+FOXP3+ Tregs and other T cells with clinical outcome in epithelial ovarian cancer patients, since this approach of triple staining has not been done in ovarian tumors to the best of our knowledge." (PMID 24244610, 2013). "Thus, immunotherapy strategies that modify the ratio of CD4+CD25+FOXP3+ Tregs or CD4+CD25+FOXP3- T cells to CD8+ effector cells may be useful in improving outcomes in ovarian cancer." (PMID 24244610, 2013). "A few years later, Sato and colleagues failed to see any direct association of CD25+FOXP3+ T cells in ovarian cancer, but did show that low total CD8+ T cell counts and the CD8+/CD25+FOXP3+ T cell ratio were associated with poorer survival, again in a population with varying histologies." (PMID 24244610, 2013). "FoxP3 is a well-recognized marker of T reg cells, and contrary to some reports, FoxP3 expressing cells have been associated with favorable patient survival, while T regs have been associated with negative patient outcomes in ovarian carcinoma due to their role in actively suppressing T cells." (PMID 24376535, 2013). "However, the CD4+CD25+FoxP3+ Tregs suppress tumor-specific T-cell immunity and increased Tregs in the tumor micro-environment can be related to the disease severity and poor outcome of ovarian carcinoma." (PMID 23082146, 2012). "Quantitative analysis showed significant downregulation of FOXP3 and EGFR mRNA expression in SKOV3 ovarian cancer cells after 48 h of treatment with Hes, ADR, and their combination (Hes + ADR) at IC50 concentrations." (PMID 41301890, 2025). "RT-qPCR and protein expression results showed that TQ and Dox can provide active treatment in ovarian cancer via the EGFR and FOXP3 signaling pathways." (PMID 40172364, 2025). "Although other oncogenic and tumor-suppressive genes were predicted in silico, FOXP3 and EGFR were prioritized for their dual mechanistic relevance and translational potential as therapeutic markers in ovarian cancer." (PMID 41301890, 2025). "A subcluster of terminal Tex cells from ovarian cancer express FOXP3, a dominant transcription factor in Treg cells, and these CD8+FOXP3+ T cells shared TCRs with CXCL13+ cells." (PMID 38519500, 2024).